BRAF (B-Raf proto-oncogene, serine/threonine kinase)
Diseases named in the same sentence as BRAF in open-access papers (continued):
Sharing a sentence is not in itself a finding about the gene and the disease.
anaplastic thyroid cancer (continued). "Remarkably, there is now an FDA approved treatment for BRAF-mutated patients with anaplastic thyroid cancer, previously considered invariably and rapidly fatal." (PMID 34335481, 2021). "The BRAF inhibitor dabrafenib and MEK inhibitor trametinib have achieved great success in BRAF V600E-mutated anaplastic thyroid carcinoma (ATC)." (PMID 34322384, 2021). "Studies that reported higher percentage of BRAF mutations in anaplastic thyroid cancer used poor sensitive detection technologies." (PMID 22654559, 2011). "BRAF V600E mutation is reported in approximately only 25% of anaplastic thyroid cancer suggesting that other genetic markers contribute to tumor progression." (PMID 22654559, 2011). "For patients with anaplastic thyroid carcinoma harboring the BRAF V600E mutation, the combination of dabrafenib (a BRAF inhibitor) and trametinib (a MEK inhibitor) provides an important targeted option, dramatically improving outcomes in a disease that previously had a dismal prognosis." (PMID 41228293, 2025). "Indeed, we report that diclofenac—a well-studied and clinically safe and approved drug—restrains the glycolytic phenotype of BRAF-mutated papillary and anaplastic thyroid carcinoma cells, opening new relevant clinical perspectives for these tumours." (PMID 37198319, 2023). "Therefore, this study further elucidated the involvement of the BRAF V600E mutation in papillary and anaplastic thyroid cancer cells and provided a new intervention target for the BRAF V600E mutation in cancer." (PMID 35748101, 2022). "Therefore, it is necessary to find new targets for the treatment of papillary and anaplastic thyroid cancer cells with BRAF mutations." (PMID 35748101, 2022). "Similarly, for anaplastic thyroid cancer with BRAF V600E mutation, dabrafenib was also recommended together with trametinib." (PMID 36545327, 2022). "This case demonstrates the possible benefit of dabrafenib/trametinib combination therapy for some patients with anaplastic thyroid carcinoma who harbor BRAF V600E mutation and highlights some characteristic side effects of targeted therapy with BRAF/MEK inhibition with pyrexia and uveitis." (PMID 35106230, 2021). "Likewise, DEL-22379 displays activity in other ERK2 dimerization-related functions, such as in memory reconsolidation and synaptic plasticity, inhibiting hippocampal ERK2 dimerization in EGF-stimulated in vivo results; or in anaplastic thyroid cancer induced by BRAF mutation." (PMID 41373638, 2025). "METHODS: In vitro, ex vivo, and in vivo models of anaplastic thyroid cancer (ATC) were used to evaluate the anticancer activity of combination BRAF inhibition and ferroptosis induction." (PMID 41501927, 2026). "Nevertheless, combination therapy with a BRAF inhibitor and MEK inhibitor has shown encouraging efficacy in patients with BRAF V600E-mutated anaplastic thyroid cancer." (PMID 40163699, 2025). "The combination of dabrafenib and trametinib is FDA approved for BRAF V600E-mutant anaplastic thyroid carcinoma based on its significant survival benefits." (PMID 41368991, 2025). "Anaplastic thyroid cancer (ATC) is another malignancy that harbors BRAF mutations in 25–45% of cases, and BRAF-targeted therapies have shown efficacy in this aggressive malignancy with a PFS around 6 months in a recent meta-analysis." (PMID 38814411, 2024).
anaplastic thyroid cancer (continued). "TERTp mutations, as a late event in tumor progression, can also occur simultaneously with BRAF or RAS mutations in poorly differentiated and anaplastic thyroid cancers, enhancing tumor aggressiveness." (PMID 39473507, 2024). "The following co-cited articles involved an open-label trial of dabrafenib (a BRAF inhibitor) and trametinib (a MEK inhibitor) combination therapy in BRAF V600E-mutated anaplastic thyroid cancer." (PMID 38420016, 2024). "Recent genomic landscape analysis of TCHA have also shown that BRAF mutations occur in around 60% of PTC and 45% of ATC (Anaplastic thyroid carcinoma) regarding as driving mutations." (PMID 39227612, 2024). "Anaplastic thyroid carcinoma, BRAF non-V600, NRAS, combination immunotherapy and targeted therapy, case report." (PMID 37122752, 2023). "In addition, the BRAF inhibitor vemurafenib has been approved for the treatment of patients with Erdheim-Chester disease with BRAF V600 mutations and the combination of dabrafenib and trametinib is approved for treatment of anaplastic thyroid cancer with BRAF V600E mutations." (PMID 36275468, 2022). "Our results showed that levels of phosphorylated GSK were increased in papillary and anaplastic thyroid cancer cells overexpressing BRAF V600E." (PMID 35748101, 2022). "The combination of the BRAF inhibitor dabrafenib and the MEK inhibitor trametinib showed an overall response rate of 69% in patients with BRAF V600E-mutated anaplastic thyroid cancer." (PMID 35522270, 2022). "We found that the protein levels of BRAF V600E were significantly decreased in BRAF V600E mutant papillary and anaplastic thyroid cancer cells." (PMID 35748101, 2022). "The results showed that BRAF WT and BRAF V600E were overexpressed in papillary and anaplastic thyroid cancer cells when infected with adenoviruses overexpressing BRAF WT and BRAF V600E." (PMID 35748101, 2022). "We next tried to understand the mechanism of BRAF V600E inhibiting the death of papillary and anaplastic thyroid cancer cells." (PMID 35748101, 2022). "To further explore the role of BRAF V600E in regulating death in papillary and anaplastic thyroid cancer cells, we constructed a BRAF WT and BRAF V600E overexpression adenovirus." (PMID 35748101, 2022). "The US FDA recently approved the combination of dabrafenib (a BRAF inhibitor) and trametinib (a MEK inhibitor) for treating BRAFV600E-mutated anaplastic thyroid cancer." (PMID 34298699, 2021). "The most common driver mutations for anaplastic thyroid cancer occur in the BRAF or RAS genes, and drugs that target the BRAF kinase have had higher response rates than cytotoxic chemotherapy." (PMID 33669447, 2021). "For BRAF-mutant DTC or anaplastic thyroid cancer (ATC), treatment with inhibitors targeting BRAF and MEK are important advances." (PMID 33569345, 2021). "The FDA-approved BRAF/MEK inhibitor combination of dabrafenib and trametinib has revolutionized treatment of BRAFV600E mutation positive anaplastic thyroid cancer." (PMID 32751138, 2020). "Following the success of the Phase II clinical trials, dabrafenib has been approved for the treatment of V600E mutant-BRAF NSCLC (NCT01336634) and BRAF+ anaplastic thyroid cancers (NCT01723202)." (PMID 30975211, 2019). "c-Met-mediated reactivation of the PI3K/AKT pathway contributes to the drug resistance to PLX4032 in BRAF (V600E) mutant anaplastic thyroid cancer cells and further promotes tumor cell migration and invasion by upregulated EMT mechanism." (PMID 27880942, 2017). "Previously, the authors have identified that c-Met mediates reactivation of the PI3K/AKT pathway following BRAF inhibitor treatment in BRAF (V600E) mutant anaplastic thyroid cancer, thereby contributing to the acquired drug resistance." (PMID 27880942, 2017).
anaplastic thyroid cancer (continued). "Among the 11 cases of anaplastic thyroid carcinomas (ATC), three showed positive results for the BRAF mutation." (PMID 23946802, 2013). "In advanced cases, such as anaplastic thyroid cancer (ATC), recent therapeutic developments have focused on mutation-specific inhibitors - such as dabrafenib and trametinib for B-Raf proto-oncogene (BRAF)-mutated ATC - as well as immune checkpoint inhibitors, aiming to enhance clinical outcomes." (PMID 40843353, 2025). "Targeting BRAF-V600E mutations with a combination of Dabrafenib and Trametinib has shown promising results and was approved by the Food and Drug Administration (FDA) as a first-line therapy for advanced or metastatic anaplastic thyroid cancer." (PMID 41436662, 2025). "Subsequently, we investigated whether BRAF V600E is involved in the regulation of mPTP opening in papillary and anaplastic thyroid cancer cells after STS exposure." (PMID 35748101, 2022). "Taken together, these results indicate that BRAF V600E deletion could aggravate papillary and anaplastic thyroid cancer cell death induced by STS exposure." (PMID 35748101, 2022). "Taken together, these results indicated that overexpression of BRAF V600E could attenuate papillary and anaplastic thyroid cancer cell death induced by STS exposure." (PMID 35748101, 2022). "Conversely, the combination of the BRAF inhibitor dabrafenib and the MEK inhibitor trametinib showed promising results and tolerability in BRAF exon 15 p.V600E-mutated unresectable or metastatic anaplastic thyroid carcinoma patients and obtained FDA approval." (PMID 33260892, 2020). "Additionally, molecular evidence points to BRAF and RAS mutations as the main drivers in poorly differentiated and anaplastic thyroid carcinoma." (PMID 27774331, 2016). "All thyroid neoplasm samples were tested for the presence of BRAF V600E mutation, which was reported to be prevalent in papillary and anaplastic thyroid carcinomas, unlike in FTC and benign thyroid nodules." (PMID 26960768, 2016). "In general, BRAF gene mutations occur more frequently in sporadic papillary thyroid carcinomas (PTCs) such as aggressive microcarcinomas and tall-cell variant cancers in adult patients, followed by poorly differentiated carcinomas and PTC-derived anaplastic thyroid carcinomas (ATCs)." (PMID 38539548, 2024). "Moreover, overexpression of BRAF V600E rather than BRAF WT in papillary and anaplastic thyroid cancer cells delayed the loss of calcein fluorescence after STS treatment." (PMID 35748101, 2022). "Consider it necessary to examine these two molecular pathways for anaplastic thyroid carcinoma because BRAF and MEK inhibitors have been shown beneficial in treating anaplastic thyroid carcinoma in numerous prior clinical trials." (PMID 38737660, 2024). "Above results suggested that BRAF V600E was localized to the mitochondria and significantly inhibited mPTP opening during STS‐induced papillary and anaplastic thyroid cancer cell death." (PMID 35748101, 2022). "In our study, we revealed for the first time that BRAF V600E promotes phosphorylation of ERK in papillary and anaplastic thyroid cancer mitochondria." (PMID 35748101, 2022). "Induced BRAF V600E expression attenuated STS‐induced papillary and anaplastic thyroid cancer death, while BRAF V600E knockdown aggravated it." (PMID 35748101, 2022). "As a selective inhibitor of BRAF kinase, dabrafenib has shown potent anti‐tumour activities in patients with BRAFV600E mutant anaplastic thyroid cancer." (PMID 32935463, 2020). "Targeted agents directed against VEGF-R like axitinib (AG-013736) or against BRAF and VEGF-R like sorafenib (Nexavar®) have been tested in phase II trials including patients with anaplastic thyroid carcinoma." (PMID 22044775, 2011). "Previous studies have found the BRAF T1799A mutation in approximately 45% of PTC and 25% of apparently PTC-derived anaplastic thyroid cancers, but not in follicular thyroid cancer (FTC) and benign thyroid tumors." (PMID 39335579, 2024).
anaplastic thyroid cancer (continued). "Our results showed that the overexpression of BRAF V600E rather than BRAF WT reduced death of papillary and anaplastic thyroid cancer cells exposed to STS compared with the negative control group." (PMID 35748101, 2022). "The results of flow cytometry‐based measurement of apoptosis and necrosis using Annexin V‐FITC/PI staining further confirmed overexpression of BRAF V600E rather than BRAF WT attenuated death in papillary and anaplastic thyroid cancer cells exposed to STS." (PMID 35748101, 2022). "We subsequently examined whether BRAF V600E‐based attenuation of STS‐induced papillary and anaplastic thyroid cancer cell death was due to the prevention of mPTP opening." (PMID 35748101, 2022). "To further confirm the relationship between BRAF V600E and cell death in papillary and anaplastic thyroid cancer cells, we knocked down endogenous BRAF V600E in the BRAF V600E mutant 8505C and BCPAP papillary and anaplastic thyroid cancer cells." (PMID 35748101, 2022). "All these data indicated that the combinational use of melatonin and BRAF‐targeting agent dabrafenib has the potential to become a novel approach in the treatment of anaplastic thyroid cancer." (PMID 32935463, 2020). "However, the combination of melatonin and BRAF‐targeting agent dabrafenib for the treatment of anaplastic thyroid cancer has not been reported." (PMID 32935463, 2020). "As of May 2019, the FDA has approved a total of three BRAF/MEK combination regimens, with the dabrafenib and trametinib combination being indicated for the treatment of BRAF-V600-positive melanoma, non-small cell lung cancer and anaplastic thyroid cancer." (PMID 31480389, 2019).
pancreatic cancer (130 papers, 2009 to 2026). "A phase II trial (NCT04390243) is currently underway to assess the efficacy of the combination therapy with binimetinib and encorafenib in pancreatic cancer patients with with a somatic BRAF V600E mutation." (PMID 41367868, 2025). "BRAF mutations are relatively rare in pancreatic tumors, previously observed at a frequency of 2% and occurring at a rate of 6% in our patient population." (PMID 39123450, 2024). "Patients with KRAS wild‐type disease and early‐onset pancreatic cancer (EOPC) harbored actionable mutations including BRAF, EGFR, ERBB2, and MAP2K1/2.PGVs in PALB2, BRCA2, and ATM were associated with high PDAC risk in the Chinese population." (PMID 36999792, 2023). "Patients with KRAS wild‐type disease and early‐onset pancreatic cancer (EOPC) harbored actionable mutations including BRAF, EGFR, ERBB2, and MAP2K1/2." (PMID 36999792, 2023). "In gastrointestinal cancers and pancreatic cancers driven by KRAS/BRAF mutation, GLI-1 is over-activated." (PMID 37304485, 2023). "Preclinical data consistently indicate that inhibition of the RAS-RAF-MEK-ERK pathway results in an increased autophagy dependence in cancers driven by KRAS or BRAF mutations (90% of pancreatic cancer)." (PMID 34439102, 2021). "We found a link between the most frequently mutated oncogenes in various cancer types, e.g., KRAS mutations in pancreatic cancer and BRAF mutations in skin cancer and the degree to which cancer cells depended on functional versions of these genes for survival." (PMID 33398072, 2021). "The existence of a subset of BRAF-mutant pancreatic tumours encoding constitutively active mutant B-Raf, 3% of pancreatic tumours, has led to the development of targeted therapeutics." (PMID 33546207, 2021). "The trial NCT04390243 is looking at binimetinib combined with encorafenib (a BRAF inhibitor) for the treatment of pancreatic cancer patients with somatic BRAF V600E mutations." (PMID 33546207, 2021). "Mutations of KRAS and BRAF are mutually exclusive in pancreatic cancers, which suggest that the activating mutations of these genes can compensate for each other in pancreatic cancer phenotypes." (PMID 25699241, 2015). "Importantly, BRAF V600E-driven pancreatic cancers should be susceptible to specific BRAF inhibitors." (PMID 38607041, 2024). "Finally, TAK-632 showed MAPK inhibitory effects with loss of pERK in a SND1:BRAF fusion pancreatic cancer model." (PMID 28002790, 2017). "Thus, pancreatic tumor growth in wild-type mice is impaired by loss of BRAF." (PMID 33674596, 2021). "In colorectal and pancreatic cancers, additional co-mutations in KRAS (non-G12C alleles), EGFR, PIK3CA, BRAF, and MAP2K1 are frequently detected at baseline and are linked to primary resistance, underscoring the importance of comprehensive NGS at diagnosis." (PMID 40940900, 2025). "It has also been shown that intratumoral injection of OBP-702 exhibits antitumor effect in subcutaneous and orthotopic tumor models with human pancreatic cancer cells harboring in-frame BRAF deletion." (PMID 37972012, 2023). "There have been few studies on the role of BRAF as a marker in pancreatic cancer, but it is foreseeable that BRAF is of great significance for guiding the diagnosis, prediction/prognosis and treatment of KRAS-WT patients." (PMID 37304241, 2023). "One study reported BRAF in-frame deletions in ~1% of human pancreatic carcinomas, of which 11 were of the ∆NVTAP type." (PMID 37079639, 2023).